EZH2 (enhancer of zeste 2 polycomb repressive complex 2 subunit)
Diseases named in the same sentence as EZH2 in open-access papers (continued):
Sharing a sentence is not in itself a finding about the gene and the disease.
melanoma (continued). "The enzyme EZH2, which catalyzes H3K27me3, is often overexpressed in melanoma and is linked to a dismal prognosis." (PMID 39199614, 2024). "Upregulation of EZH2 is robustly associated with highly proliferative and aggressive melanoma subtypes, and has been shown to increase incrementally from benign nevi to melanoma and invasive subtypes as shown by immunohistochemical analysis." (PMID 39624739, 2024). "New research has shown that enhancer of zeste homolog 2 (EZH2) is activated or overexpressed by mutations in melanoma and other tumors, resulting in the silencing of antigen presentation-related genes and cancer suppressor genes." (PMID 38665224, 2024). "For example, the EZH2 enzyme’s methylation of histone H3 on lysine 27 (H3K27me3) has been linked to the development of melanoma and the silencing of genes." (PMID 39199614, 2024). "It has been shown that in melanoma, breast, prostate, and endometrium cancer, upregulation of EZH2 is associated with a high proliferation index." (PMID 38339397, 2024). "Here the authors report that Mi-2β promotes immune evasion by activating EZH2 methylation and that loss of Mi-2β or its inhibition promote anti-tumor immune responses in preclinical melanoma models." (PMID 38461299, 2024). "In a melanoma mouse model, EZH2 was associated with the epigenetic development of resistance against recombinant IL-2 (rIL2) and ICI." (PMID 37394580, 2023). "EZH2 and other PRC2 components are frequently amplified or overexpressed in melanoma, and several activating EZH2 mutations such as various mutations of tyrosine Y641 have been identified." (PMID 37325482, 2023). "Several mutations activating EZH2 have been identified in melanoma, which contributes to aberrant gene silencing during tumor progression." (PMID 37325482, 2023). "The BRAFV600E mutation is linked to a high expression of EZH2, which is associated with melanoma progression and worse patient overall survival." (PMID 36768289, 2023). "EZH2 has received increased attention as a cause of resistance in tumor immunotherapy because it is overexpressed in various cancer types, including melanoma, and silences tumor-suppressor genes or genes associated with antigen presentation." (PMID 37394580, 2023). "Treatment of various BRAF-mutated melanoma cell lines with the BRAF inhibitor dabrafenib (GSE98314) reduced the expression of EZH2 and PLK1 in a comparable manner." (PMID 36768289, 2023). "In our previous work, we noticed decreasing levels of EZH2 in BRAFV600E-mutated melanoma cells treated with vemurafenib, while cells resistant to BRAF inhibitors showed an unchanged expression of EZH2 upon treatment with vemurafenib." (PMID 36768289, 2023). "High expression and activity of EZH2 have been linked to worse prognosis and shorter survival of melanoma patients." (PMID 37325482, 2023). "Increased expression of EZH2 has been associated with elevated level of Yin Yang 1 (YY1) transcription factor in melanoma TILs." (PMID 37325482, 2023). "An inverse association between melanoma cell pigmentation and EZH2 protein was observed in vivo in PDX melanomas." (PMID 36906655, 2023). "In total, 3% of melanomas are associated with activating mutations in EZH2, with a role in melanoma progression." (PMID 36614156, 2022). "Melanoma suffers from decreased immunogenicity and loss of antigen presentation when the expression of EZH2 is increased." (PMID 36384676, 2022). "In our system, H3.3K27M accelerated melanoma onset, but activating EZH2 mutations have been shown to promote melanoma onset in mice." (PMID 35223844, 2022). "The most important methyltransferase with a role in melanoma is EZH2 (Histone-lysine N-methyltransferase EZH2) encoded by the EZH2 gene (enhancer of zeste 2 polycomb repressive complex 2 subunit)." (PMID 36614156, 2022). "An analysis of EZH2 point mutations identified the presence of gain-of-function Y641 substitutions and reduced activity P132S mutations in a small percentage of melanoma cases." (PMID 35223844, 2022).
melanoma (continued). "Inhibition of EZH2 with the specific inhibitor EPZ-6438 (EPZ) significantly increased miR-129-5p expression in BRAF mutated melanoma cell lines (A375, WM35), even in BRAFi resistant cell lines (A375R, WM35R)." (PMID 34063443, 2021). "Examinations of Human Protein Atlas datasets revealed that overexpression of BET family BRD proteins (i.e., BRD2 and BRD3), BRD9, BRD7, and EZH2 were associated with relatively poor three-year survival in melanoma patients." (PMID 34771678, 2021). "Some authors have shown that EZH2 expression is associated with the suppression of senescence in human melanoma cells." (PMID 34575678, 2021). "The role of the histone methyltransferase EZH2 in driving transformation from benign to malignant melanoma has been associated with the regulation of both the cell cycle and ciliogenesis." (PMID 34359832, 2021). "In particular, increased activity of the histone methyltransferase EZH2 has been associated with various cancers, including melanoma." (PMID 33849069, 2021). "In the past years, extensive studies have implicated EZH2 in the development and progression of various malignancies including prostate cancer, breast cancer, endometrial cancer and melanoma." (PMID 33849069, 2021). "A melanoma EZH2 mouse model showed that melanocyte specific loss of EZH2, or treatment with an EZH2 inhibitor, abolished the spread of metastatic melanoma." (PMID 34220955, 2021). "Heterozygous activating mutations of EZH2 are found in germinal center-type diffuse large B cell lymphoma and more rarely in thyroid cancer and malignant melanoma." (PMID 34001289, 2021). "EZH2 is often overexpressed in human melanoma, driving melanoma de-differentiation and loss of immunogenicity, and EZH2 inhibition synergized with immunotherapy in a mouse model of melanoma." (PMID 34201655, 2021). "In melanomas, the most frequent hotspot mutations in EZH2 are in the enzymatic SET-domain Y641, and the frequency of different EZH2 mutations in melanomas is approximately 5%." (PMID 34831002, 2021). "After treatment of BRAF mutated melanoma cells with BRAFi or MEKi, we observed a reduction of EZH2 protein as well as mRNA for melanoma." (PMID 34063443, 2021). "A recent study also found that EZH2 induced loss of primary cilia, enhanced Wnt signaling and promoted melanoma metastasis." (PMID 34220955, 2021). "On the other hand, in EZH2 overexpressing melanoma cells, the EZH2 inhibitor GSK126 caused caspase-independent apoptosis, mediated by apoptosis-inducing factor, mitochondrion associated 1 (AIFM1) protein." (PMID 34947882, 2021). "Elevated expression of EZH2 was already shown to be associated with poor prognoses in melanoma patients." (PMID 34440824, 2021). "For example, Zingg at al. observed that anti-CTLA-4 or IL-2 immunotherapy leads to TNFα amplification and T cell infiltration, resulting in EZH2 overexpression and loss of tumor control in melanoma mouse models." (PMID 34575678, 2021). "Further analysis of previous sequencing results showed that EZH2 mutations in human melanoma co-occur with activating mutations in BRAF (p = 0.006) and are mutually exclusive with NRAS mutations (p = 0.004)." (PMID 33024276, 2020). "In several cancers, including melanoma, EZH2 is overexpressed or activated by mutation, leading to silencing genes associated with antigen presentation or tumor-suppressor genes." (PMID 32708698, 2020). "A comprehensive analysis of 471 melanoma patients in the TCGA dataset revealed hyperactivation of EZH2 associated with a downregulation of immune response genes in approximately 20% of melanoma patients." (PMID 32041674, 2020).
melanoma (continued). "Our study shows that H3K27me3 expression is more frequent than EZH2 and is associated with a more invasive and metastatic melanoma cell phenotype." (PMID 32041674, 2020). "Increasing research has indicated that EZH2 is widely associated with carcinomas, such as hepatocellular carcinoma, colorectal cancer, melanoma and neuroendocrine tumors." (PMID 33297932, 2020). "Another example of a functional association between mutation/overexpression and melanoma initiation and progression is the chromatin modifier EZH2." (PMID 33024276, 2020). "We also examined the association of age with the high KDM6A and low EZH2 group since it has been reported that the improved survival of female melanoma patients only applies to those below 60 years of age." (PMID 32731355, 2020). "A375 cells with lncRNA GAS5 silencing were added with DMSO or UNC1999 and the biological changes associated with melanoma cells were investigated by inhibiting the EZH2 expression and H3K27 methylation." (PMID 32308561, 2020). "Overexpression and gain-of-function mutations of EZH2 are typical for many cancers, including melanoma." (PMID 32466509, 2020). "Upregulation of the histone methyltransferase enzyme EZH2 and its histone modification H3K27me3 has been linked to melanoma progression, metastasis, and resistance to immune checkpoint blockade (ICB)." (PMID 32041674, 2020). "Similar to IDH1, EZH2, a member of polycomb repressive complex 2, is another recurrent site of gain-of-function mutations in melanoma, although at a lower frequency." (PMID 33024276, 2020). "One study identified previously unreported recurrent activating mutations (e.g., G1069) in EHMT2, as well as EHMT2 copy number gains in ~26% of human melanomas, which is similar to the pattern of EZH2 gain-of-function mutations." (PMID 33024276, 2020). "A previously reported study has revealed that EZH2 exhibits high expression in melanoma and is associated with its development." (PMID 32308561, 2020). "It has been shown experimentally that T cell infiltration promotes H3K27me3 and EZH2 upregulation in melanoma cells, resulting in loss of immunogenicity and antigen presentation." (PMID 32041674, 2020). "A significant increase in melanoma apoptosis, compared to treatment with single agents, was obtained even by association of EZH2 inhibitor GSK126 with the GSK-3β inhibitor AR-014418, in agreement with the role of GSK-3β in NFATc2 regulation." (PMID 30710146, 2019). "Taken together these results indicate that NFATc2 and EZH2 represent potentially relevant actionable targets in melanomas belonging to different mutational subsets." (PMID 30710146, 2019). "Increased expression of EZH2 is associated with melanoma progression and decreased overall patient survival." (PMID 30466474, 2018). "The epigenetic modulator EZH2 was also investigated as it has recently been linked to melanoma invasion and metastasis, and has been previously identified as a target of NFIB in neuronal cell lineages." (PMID 28119061, 2017). "H3K27me3 is a repressive mark catalyzed by the lysine methyltransferase EZH2, which is implicated in the pathogenesis and progression of various cancers, including melanoma." (PMID 28400597, 2017). "As in several other cancers, EZH2 is overexpressed in the progression of benign nevi to invasive or metastatic melanoma, and acquired functional mutations in EZH2 account for 3% of melanomas." (PMID 28415635, 2017). "Hyperactivation of EZH2 by somatic mutations or copy number gain occurs in 20% of melanoma patients and negatively impacts overall survival." (PMID 28265786, 2017). "In this study, we indicated that coexistence of BRAF V600E mutation and EZH2 gain is rather prevalent in melanoma." (PMID 29202777, 2017).
melanoma (continued). "Combination with BRAF and EZH2 inhibition showed better inhibitory efficacy compared with vemurafenib monotherapy in vitro and in vivo, especially in melanoma containing concurrently BRAF V600E mutation and EZH2 gain." (PMID 29202777, 2017). "EZH2 overexpression is associated with aggressiveness and worse prognosis in prostate, breast, bladder, endometrial tumors, melanoma and GBM." (PMID 27449082, 2016). "CDKN1A has been previously implicated as an EZH2 target gene in melanoma and other cancers and can promote G2/M arrest." (PMID 26304929, 2015). "As such, the simultaneous inhibition of both BRAF and EZH2 should be considered in treatment of melanoma patients that harbor these mutations." (PMID 25671303, 2015). "To assess the therapeutic implications of our findings in the A375 model, we next extended our studies to the IGR1 melanoma cell line that contains an endogenous EZH2 GOF mutation (Y641N)." (PMID 25671303, 2015). "Collectively these studies are the first to demonstrate that human melanoma cells with activating mutations in EZH2 display a critical dependency on this enzyme for their growth and survival." (PMID 26304929, 2015). "Activating mutations in EZH2 are found in a subset of melanoma that contributes to disease progression by inactivating tumor suppressor genes." (PMID 26304929, 2015). "Recently, a comprehensive analysis of driver mutations in melanoma has revealed the presence of EZH2 GOF mutations (2%) within this disease setting." (PMID 25671303, 2015). "High levels of EZH2 were associated with increased proliferation (Ki-67 staining), thicker primary melanomas, increased invasion and poor survival." (PMID 26304929, 2015). "Genetic and epigenetic loss of miR-31 is associated with EZH2 overexpression in melanoma, suggesting that miR-31 directly or indirectly regulates EZH2 expression." (PMID 25644061, 2015). "A375 is a malignant skin melanoma cell line that harbors an activating BRAF mutation and was chosen based on the observation that EZH2 GOF mutations have been shown to occur concurrently with BRAF mutations in melanoma." (PMID 25671303, 2015). "EZH2 has been shown to promote tumor cell proliferation and is associated with a high proliferation index in many types of cancer, including breast, prostate, endometrium, and melanoma." (PMID 38339397, 2024). "In melanoma, EZH2 represses genes associated with tumor suppression, cell differentiation, cell cycle inhibition, metastasis, and antigen processing and presentation, and is upregulated transcriptionally by E2F and c-myc and suppressed by differentiation-promoting factors such as pRb and p16INK4b." (PMID 36906655, 2023). "Point mutations of EZH2 result in a gain-of-function in 5% of melanomas and are often found in coexistence with activating BRAF mutations, which may indicate an oncogenic synergism." (PMID 37370834, 2023). "Indeed, we found that EZH2 protein was inversely associated with pigmentation in both melanoma cells and patient melanomas." (PMID 36906655, 2023). "Our studies extend understanding of this oncoprotein by demonstrating UHRF1/UBE2L6/UBR4-mediated EZH2 promotion to enhance LPC phenotypes and disease progression in melanoma, providing a mechanism as to how higher levels of EZH2 are associated with late-stage disease." (PMID 36906655, 2023). "Moreover, EZH2 overexpression is associated with poor survival in melanoma patients and its deletion results in slower tumor progression." (PMID 35203421, 2022). "The epigenetic regulator EZH2, was recently shown to coordinate melanoma cell dedifferentiation (associated with a gain in ZEB1 and NGFR) with downregulation of MHC class I (HLA-A/B/C) and antigen presentation machinery (i.e. antigen processing genes TAP1/2 and immunoproteasome subunits PSMB8/9)." (PMID 35432344, 2022). "Of note EZH2 was also shown as a mediator of treatment resistance in BRAF mutated melanoma." (PMID 34063443, 2021).
melanoma (continued). "Reanalysis of a published dataset (GSE98314) revealed that treatment with the BRAFi Dabrafenib decreased EZH2 expression in 11 different BRAF mutated melanoma cell lines and we found a significant inverse correlation of EZH2 and miR-129 expression (r = −0.46; p = 0.029)." (PMID 34063443, 2021). "Additionally, specific inhibition of EZH2 induces miR-129-5p expression in BRAF mutated melanoma cell lines, independent from their BRAFi response status, while BRAF wildtype cells and normal melanocytes show no changes of expression." (PMID 34063443, 2021). "Additionally, the subset of the BRAF mutated melanoma cohort of the cancer genome atlas (TCGA) harboring an EZH2 silent mutation, showed a highly significant enforced miR-129-5p expression compared to BRAF mutated melanoma patients with EZH2 wildtype." (PMID 34063443, 2021). "The main role of KDM6A/B may be as an antagonist of EZH2 which has been implicated in the growth and progression in melanoma." (PMID 34220955, 2021). "In addition, EZH2 can increase melanoma growth and is associated with a high proliferation rate through the silencing of tumor suppressors." (PMID 34831002, 2021). "EZH2 is a well-known oncogene associated with a more aggressive form and poorer prognosis of many cancers, including melanoma, squamous cell carcinoma (SCC), and BCC, with demonstrated increased expression in SCC [compared to normal skin and SCC precursor actinic keratosis (AK)] and aggressive BCC." (PMID 34900699, 2021). "However, miR-129-5p expression was elevated in BRAF mutated melanoma patients harboring EZH2 missense or silencing mutations compared to wildtype EZH2." (PMID 34063443, 2021). "EZH2-deficient CD8 + T cells were incapable of mediating tumor growth inhibition to the same degree as EZH2-sufficient cells when transferred into mice with preestablished B16-melanoma." (PMID 34001289, 2021). "Of note, coexistence of BRAF V600E mutation and EZH2 amplification is rather prevalent in melanoma." (PMID 32850962, 2020). "All of these studies confirmed the occurrence of EZH2 mutation and overexpression in melanoma." (PMID 33024276, 2020). "In human melanoma cells, loss of EZH2 partially interfered with invasion capacity." (PMID 31959200, 2020). "Indeed, in a cohort of 138 patients with BRAF V600E-mutated melanoma, 40 cases (29.0%) showed EZH2 gain." (PMID 32850962, 2020). "The EZH2-dependent expression of genes associated with cell motility contributes to early phases of metastasis while activating variants promotes melanoma progression inactivating tumor suppressor genes." (PMID 32850962, 2020). "EZH2 expression is elevated and associated with poor survival in melanoma." (PMID 32042336, 2020). "This hypothesis is already supported by the fact that the chromatin modifier EZH2, which is commonly mutated or overexpressed in melanoma, has been shown to drive structural changes in chromatin domains in diffuse large B-cell lymphoma." (PMID 33024276, 2020). "Based on this above discussion, we hypothesized that lncRNA GAS5 acts as a suppressor in melanoma and its underlying mechanism could involve EZH2 and CDKN1C." (PMID 32308561, 2020). "In addition, we chose to study two major epigenetic regulators, DNMT1 (DNA methyltransferase 1) and EZH2 (enhancer of zeste homologue 2), since high levels of expression have been associated to melanoma aggressiveness." (PMID 30651148, 2019). "In addition, expression of Ezh2Y641F, the most common somatic EZH2 mutation (Y646F in human, Y641F in the mouse), in mouse melanocytes causes melanoma through a vast reorganization of chromatin structure." (PMID 31921860, 2019). "In addition, in various melanoma cell lines, Tyr641 mutations of EZH2 have shown to alter the substrate specificity of EZH2 to H3K27me2, causing an increase in H3K27me3 and depletion of H3K27me2." (PMID 30466474, 2018). "The emphasis of EZH2 in melanoma is enhanced by specific loss of other KTMs." (PMID 28265786, 2017).